UNC5A (unc-5 netrin receptor A)
Diseases named in the same sentence as UNC5A in open-access papers (continued):
Sharing a sentence is not in itself a finding about the gene and the disease.
breast tumors (1 paper, 2018). "Consistent with in vitro results, UNC5A expression negatively correlated with EGFR expression in breast tumors, and lower expression of UNC5A, particularly in ERα+/PR+/HER2− tumors, was associated with poor outcome." (PMID 29720215, 2018). "Similarly, UNC5A and EGFR expression showed negative correlation in breast tumor samples when the analyses included all samples or only ER+ samples." (PMID 29720215, 2018).
diffuse large B-cell lymphoma (1 paper, 2022). "UNC5A expression correlated positively with MSI in COAD, TGCT, UVM, and ACC and negatively with HNSC, KIRC, and diffuse large B-cell lymphoma (DLBC)." (PMID 36551254, 2022).
head and neck squamous cell carcinoma (1 paper, 2022). A squamous cell carcinoma that arises from any of the following anatomic sites: lip and oral cavity, nasal cavity, paranasal sinuses, pharynx, larynx, and salivary glands. "The mutational landscape of UNC5A exhibited that patients with UNC5A mutations had poorer progress free survival (PFS) in head and neck squamous cell carcinoma (HNSC) and prostate adenocarcinoma (PRAD)." (PMID 36551254, 2022).
Morvan syndrome (1 paper, 2019). Morvan syndrome is a rare, life-threatening, acquired neurologic disease characterized by neuromyotonia, dysautonomia and encephalopathy with severe insomnia. "Amongst these, two patients showed polyreactivities that included the two Netrin‐1 receptor antibodies (CASPR2+LGI1+DCC+UNC5A and CASPR2+LGI1+DCC), both diagnosed as Morvan syndrome." (PMID 30714278, 2019).
uveal melanoma (1 paper, 2022). A melanoma derived from melanocytes of the uveal tract. "For DSS, Cox regression showed that a high UNC5A level was a risk factor for LUSC (HR = 1.17, p = 8.2 × 10−3), KIRC (HR = 1.12, p = 0.02), and uveal melanoma (UVM, HR = 1.22, p = 0.02) but a protective factor for LGG (HR = 0.63, p = 1.2 × 10−13)." (PMID 36551254, 2022).
cancer (17 papers, 2015 to 2026). A tumor composed of atypical neoplastic, often pleomorphic cells that invade other tissues. "One of the hot spot mutations of UNC5A (X674_splice) was found in three patients with three cancers (UCEC, kidney renal clear cell carcinoma [KIRC], and kidney renal papillary cell carcinoma [KIRP])." (PMID 41407823, 2025). "The results exhibited that mutation of the UNC5A gene was intimately correlated with UNC5A transcriptional expression in pan-cancer and gene gain was the most frequency CNV of UNC5A." (PMID 36551254, 2022). "Subsequently, the GSCA online website was used to elucidate the association of UNC5A expression in pan-cancer with UNC5A DNA methylation levels." (PMID 36551254, 2022). "UNC5A was found to be highly expressed across multiple human cancer tissues and cells, was linked to clinical outcomes of patients, and was a potential pan-cancer biomarker." (PMID 36551254, 2022). "SangerBox was utilized to assess the association of UNC5A levels with StromalScore and ImmuneScore in pan-cancer." (PMID 36551254, 2022). "Herein, we first assessed the relationship between the four DNA methyltransferases and UNC5A expression and found significant pan-cancer associations." (PMID 36551254, 2022). "Thus, assessing the association of UNC5A level with the DNA methylation status in cancers is of great significance." (PMID 36551254, 2022). "Herein, UNC5A was highly expressed across various human cancers tissues and cells and was linked to the clinical outcomes of patients and may serve as a potential biomarker in pan-cancer." (PMID 36551254, 2022). "Here, we investigated the roles of netrin receptors, uncoordinated-5 homologues (UNC5A, -B, -C, and -D), deleted in colorectal cancer (DCC), and the DCC paralog (neogenin) during myogenic differentiation, focusing on fast-twitch myotube formation." (PMID 41703986, 2026). "Subsequently, the association of UNC5A level with TMB, neoantigen, and MSI was evaluated, and our findings showed the UNC5A expression was related to TMB, MSI, and neoantigenin pan-cancer." (PMID 36551254, 2022). "One of the ligands of UNC5A, netrin-1 is known to be overactivated in cancers, especially in inflammation-driven tumors." (PMID 36551254, 2022). "Subsequently, we downloaded the RNA sequences from the TCGA database to further verify the expression pattern of UNC5A between adjacent normal and pan-cancer tissues." (PMID 36551254, 2022). "Our findings demonstrated a high expression of UNC5A across pan-cancers and its relationship with several clinical outcomes." (PMID 36551254, 2022). "Gene alterations in UNC5A occurred in the majority of cancer types, especially KIRC (alteration frequency was nearly 8%), and UNC5A alterations were related to the PFS of patients with HNSC and PRAD." (PMID 36551254, 2022). "The UNC5A mRNA expression profile between normal and cancer cells was assessed, and the results exhibited higher levels in cancer cells than in normal cells." (PMID 36551254, 2022). "Herein, multiple online databases and R packages were used to evaluate the role of UNC5A in human cancers." (PMID 36551254, 2022). "There was a strong association between UNC5A expression and various ICP genes in pan-cancer; for example, UNC5A expression was related to 54 out of 60 ICP genes in LGG." (PMID 36551254, 2022). "Due to the close relationship between UNC5A and netrin-1, we explored the relationship between UNC5A and tumor immunity in cancers." (PMID 36551254, 2022). "Although we comprehensively analyzed UNC5A expression in pan-cancer, some limitations warrant further consideration." (PMID 36551254, 2022). "Herein, the R software and multiple databases (including TCGA, GTEx, TIMER, GSCA, GEPIA, and cBioPortal) were used to examine UNC5A’s role in pan-cancer." (PMID 36551254, 2022). "UNC5A expression was significantly associated with MSI, TMB, neoantigen, TME, and tumor immunity in pan-cancer." (PMID 36551254, 2022).
cancer (continued). "In human cancer cells, enforced expression of UNC5A, UNC5B and UNC5C inhibits cell-anchorage growth and invasion in a way related to their pro-apoptotic activity." (PMID 33126652, 2020). "Furthermore, we downloaded and statistically analyzed MCAM and UNC5A expression, as well as immunotherapy score data from TCGA and The Cancer Immunome Atlas (TCIA) databases respectively." (PMID 41407823, 2025). "UNC5A had been reported to play crucial roles in multiple cancers." (PMID 39039366, 2024). "Among them, Cspg5, Fbn1, Thbs1, Pdpn, Etv4, Unc5a, Ntn1, and Nat8l were associated with the OC prognosis; Cspg5, Fbn1, Pdpn, and Unc5a were correlated with patient age; Fbn1, Mycn, Nat8l, Unc5a, and Ntn1 were significantly correlated with individual cancer stage." (PMID 36829196, 2023). "The immune infiltration level of UNC5A in pan-cancer was examined utilizing the TIMER database." (PMID 36551254, 2022). "Our results suggest the potential of UNC5A as a pan-cancer biomarker and an efficient immunotherapy target, which may also guide drug selection for some specific cancer types in clinical practice." (PMID 36551254, 2022). "Recently, studies have found that UNC5A may function as a tumor suppressor, affecting the onset and progression of cancers." (PMID 36551254, 2022). "Finally, we assessed the methylation status of UNC5A in pan-cancer and its correlations with drug sensitivity." (PMID 36551254, 2022). "The top ten normal and cancer cells with the highest expression of UNC5A are illustrated)." (PMID 36551254, 2022). "In summary, we present the first comprehensive role of UNC5A in pan-cancer." (PMID 36551254, 2022). "Unc5a acts as a tumor suppressor of different cancers through inhibition of cell growth." (PMID 36374852, 2022). "Thus, further investigations are needed to evaluate the potential action mechanism of UNC5A in the diagnosis and patient prognosis of cancers." (PMID 36551254, 2022). "UNC5A expression correlated negatively with UNC5A DNA methylation levels in various cancer types, hinting at the potential tumorigenesis mechanism of UNC5A action in pan-cancer." (PMID 36551254, 2022). "UNC5A is a candidate prognostic biomarker for multiple cancer types." (PMID 36551254, 2022). "Based on cell surface marker profiles and KRT14/KRT19 expression patterns in sh-UNC5A cells, we propose that the gradual loss of UNC5A results in cancer cells acquiring hybrid phenotype without expressing classic markers of EMT." (PMID 29720215, 2018). "However, only a few studies have illustrated its role in some specific cancer types, and the role of UNC5A in multiple human cancers remains unknown." (PMID 36551254, 2022). "In addition, the alteration frequency of UNC5A varied in pan-cancer." (PMID 36551254, 2022). "Finally, the UNC5A may promote tumorigenesis and progression through DNA methylation and its expression can guide drug selection for some specific cancer types in clinical practice." (PMID 36551254, 2022). "Therefore, UNC5A may serve as an effective pan-cancer biomarker." (PMID 36551254, 2022). "Subsequently, time-dependent ROC curves were plotted to examine the prognostic value of UNC5A expression in the prediction of 1-, 3-, and 5-year survival in terms of DSS, OS, and PFI in pan-cancer." (PMID 36551254, 2022). "Next, we evaluated the relationships between UNC5A expression and immunomodulators (including chemokine, receptor, MHC, immunoinhibitor and immunostimulators) and various ICP genes across cancers." (PMID 36551254, 2022). "For instance, a repertoire of axon-guidance molecules (e.g. netrin-1, UNC5A, NEO1, RGMA) have been shown to be dysregulated in human cancers, including colorectal cancer." (PMID 29459716, 2018). "UNC5A, UNC5B and UNC5C, which are the receptors of netrin 1, are all down-regulated in various cancers through promoter methylation." (PMID 26294325, 2015).
cancer (continued). "Herein, UNC5A expression was found to be significantly related to CD8+ T cells in 9 cancers, B cells in 10 diverse cancer types, CD4+ T cells in 21 cancers, macrophages in 16 cancers, neutrophils in 18 cancer types, and dendritic cells in 18 cancer types." (PMID 36551254, 2022). "UNC5A level was significantly related to the infiltration of B cells in 10 diverse cancer types, CD4+ T cells in 21 various cancer types, CD8+ T cells in 9 cancers, neutrophils in 18 cancers, macrophages in 16 cancers, and dendritic cells in 18 cancers." (PMID 36551254, 2022). "UNC5A was related to DSS, OS, DFI, and PFI in different cancer types, and could predict the 1-, 3-, and 5-year DSS, OS, and PFI in KICH and UVM." (PMID 36551254, 2022). "Second, UNC5A is highly expressed and related to clinical outcomes in pan-cancer; however, its potential mechanism of action has not yet been elucidated." (PMID 36551254, 2022). "Since ΔNp63 maintains stem cell phenotype and cancer cells with hybrid luminal/basal/mesenchymal characteristics display enhanced cancer stem cell (CSC) properties, we used mammosphere assays and flow cytometry to characterize sh-Control and sh-UNC5A MCF7 cells for stemness." (PMID 29720215, 2018). "Thus, it appears that even transient knockdown of UNC5A leads to robust/permanent activation of BCL2, which is similar to previously reported stable activation of cancer germline genes upon transient knockdown of DNA methyltransferase 1 (DNMT1)." (PMID 29720215, 2018). "Moreover, it had been shown that UNC5A had a negative feedback regulatory effect in a variety of cancers and the expression of this gene was significantly down-regulated in bladder, rectal and breast cancers, even in liver cirrhosis." (PMID 39039366, 2024). "Additionally, many of these markers, namely, KDR, FLT4, and UNC5A, have been shown to be involved in other types of cancers, making these markers non-exclusive to KS tumorigenesis." (PMID 37046832, 2023). "Finally, we evaluated the PFS of patients with or without UNC5A alterations across cancer types, and the results exhibited that patients with UNC5A alterations had a poor PFS in HNSC (p = 0.0127) and PRAD (p = 9.596 × 10−3)." (PMID 36551254, 2022). "Further, the highest alteration frequency in pan-cancer was that of copy-number variations (CNV, including amplification and deep deletions), and thus, we assessed the correlation between the putative CNV in UNC5A and the corresponding gene expression in pan-cancer." (PMID 36551254, 2022).
tumor (14 papers, 2013 to 2025). "The expression of UNC5A was associated with tumor purity (r = − 0.143), CD4 + T cells (r = 0.184), macrophages (r = 0.169), neutrophils (r = 0.189), and dendritic cells (r = 0.117)." (PMID 41407823, 2025). "In aspects of the tumor immune microenvironment, it presented significant associations with UNC5A in LGG or GBM, according to our results." (PMID 39039366, 2024). "Neoantigen, MSI, and TMB are strongly linked to tumorigenesis and progression and can predict tumor immunotherapeutic efficacy; therefore, we studied the relationships between UNC5A expression and TMB, neoantigen, and MSI." (PMID 36551254, 2022). "We further explored the associations among UNC5A and tumor immunity." (PMID 39039366, 2024). "According to our results, UNC5A presented significant associations with immune cell infiltrations in LGG and with immune checkpoints, tumor immune microenvironment, as well as immune cells in LGG or GBM." (PMID 39039366, 2024). "Among the tumor suppressor genes frequently epigenetically downregulated in CRC, the four related genes of the UNC5 family: UNC5A, UNC5B, UNC5C and UNC5D encode dependence receptors that regulate the apoptosis/survival balance." (PMID 33126652, 2020). "In breast cancer MCF7 cells, a co-regulation by OGT and EZH2 was also evidenced for 16 tumor suppressor genes including UNC5A." (PMID 33126652, 2020). "UNC5A knockdown increased the levels of oncogenic ΔNp63 isoform mRNA while simultaneously lowering the expression of tumor suppressive TAp63 isoform." (PMID 29720215, 2018). "Autopsies within 17 weeks of injection revealed growth of tumor cells in ovaries and adrenal glands at a higher frequency in animals injected with sh-UNC5A cells compared with sh-Control cells." (PMID 29720215, 2018). "Finally, in this study we found that there is a tight relationship between UNC5A and tumor immunity." (PMID 36551254, 2022). "Collectively, our data support the hypothesis that O-GlcNAcylation could represent one link between nutrition and epigenetic downregulation of key tumor suppressor genes governing colon carcinogenesis including UNC5A." (PMID 33126652, 2020). "Xenograft models were used to measure the effect of UNC5A knockdown on tumor growth and metastasis." (PMID 29720215, 2018). "Furthermore, UNC5A expression was associated with tumor mutation burden (TMB), neoantigen, tumor microenvironment (TME), tumor microsatellite instability (MSI), immunomodulators, immune infiltration, DNA methylation, immune checkpoint (ICP) genes, and drug responses." (PMID 36551254, 2022). "Increased expression of TIMP1, MMP1, AGRN, UNC5A, and ADAMTS4 was observed, while the expression of UNC5C, TINAG, SPOCK3, and ITGA7 was reduced in the normal FHC cells compared to the HCT8 tumor cells." (PMID 39011483, 2024). "The FLT4, KDR, and UNC5A proteins were detected at high levels within the L1T2 xenografts, mirroring the human KS tumor expression patterns." (PMID 37046832, 2023). "Here, in correlation with transcriptome data, we demonstrated the detectable protein expression of KDR, FLT4, UNC5A, ADAM12, CD34, and Prox-1 in the human KS tumor microenvironment." (PMID 37046832, 2023). "In summary, we detected the partial recapitulation of KS tumor microenvironment cell surface protein expression within the xenograft tissues where FLT4, KDR, UNC5A, and ADAM12 mirrored the levels detected in the human KS tumors." (PMID 37046832, 2023). "Thus, we hypothesized that UNC5A may be a key receptor involved in netrin-1-mediated tumor growth." (PMID 28710382, 2017). "The other netrin-1 receptors, UNC5A, UNC5B, and UNC5C, were also discovered as putative tumor suppressor genes in various tumors." (PMID 26207151, 2015). "Similar to DCC receptors, other netrin-1 receptors, including UNC5A, UNC5B, and UNC5C, were also discovered as putative tumor suppressor genes in various tumors, including gastric cancer." (PMID 26207151, 2015).
tumor (continued). "In order to better understand the functions that UNC5A played in tumor immunity, we mined the connections among UNC5A and immunological characteristics like TMB, MSI, TNB, tumor microenvironment, immune checkpoints, immune cell infiltrations, and immune cell pathways." (PMID 39039366, 2024). "Additionally, in aspects of tumor immunity, the infiltration levels of immune cells in LGG, the immune cell pathways, tumor immune microenvironment, as well as immune checkpoints in both LGG and GBM were revealed to be significantly influenced by UNC5A." (PMID 39039366, 2024). "Additionally, in aspects of tumor immunity, the infiltration levels of immune cells in LGG, the immune cell pathways, tumor immune microenvironment, as well as immune checkpoints in both LGG and GBM were revealed to be significantly influenced by UNC5A (p < 0.05)." (PMID 39039366, 2024). "However, how UNC5A’s relation to tumor immunity has not been elucidated, which should be further explored in future studies." (PMID 36551254, 2022). "Two drug candidates, TRAP-netrinDCC and TRAP-netrinUNC5A, which are Fc-fused and stabilized ectodomains of respectively DCC or UNC5A, have been shown to trigger death of netrin-1 expressing tumour cells in vitro and tumour growth inhibition in engrafted mice models (not shown)." (PMID 24293316, 2013). "The relationship between UNC5A expression with the majority of immunomodulators and ICP genes was significant, especially in LGG, suggesting that UNC5A may be a potential immunotherapeutic target and might serve vital functions in tumor immunotherapy responses and outcomes." (PMID 36551254, 2022).
UNC5A also shares sentences with these, for which no sentence is quoted: acute myeloid leukemia (2 papers); bladder cancer (2); astrocytoma (1); brain glioma (1); breast invasive carcinoma (1); cervical squamous cell carcinoma (1); cholangiocarcinoma (1); colon adenocarcinoma (1); colorectal tumors (1); endocervical adenocarcinoma (1); esophageal carcinoma (1); fibrosis (1); kidney chromophobe (1); lung squamous cell carcinoma (1); malignant melanoma (1); medulloblastoma (1); neuroepithelial tumors (1); nutritional disorder (1); ocular melanoma (1); Pan (1); paraganglioma (1); pheochromocytoma (1); prostate adenocarcinoma (1); prostate carcinoma (1); prostate tumors (1); rectum adenocarcinoma (1); seminoma (1); skin cutaneous melanoma (1); stomach adenocarcinoma (1); testicular germ cell tumor (1).
A further 4 diseases each share a sentence with UNC5A in 1 paper.